SERPINF1 (serpin family F member 1)
Description:
Neurotrophic protein; induces extensive neuronal differentiation in retinoblastoma cells. Potent inhibitor of angiogenesis. As it does not undergo the S (stressed) to R (relaxed) conformational transition characteristic of active serpins, it exhibits no serine protease inhibitory activity.
Synonyms: PEDF; PIG35; EPC-1; OI12; OI6
Tractability: Antibody: UniProt places it where antibodies can reach, with high confidence; its Gene Ontology location is reachable by antibodies, with high confidence; UniProt predicts a signal peptide or a membrane-spanning region. PROTAC: its protein half-life has been measured.
Gene: Protein-coding gene on chromosome 17 (1,761,979 to 1,777,627, forward strand). Ensembl gene ENSG00000132386.
Subcellular location: Secreted; Melanosome
Gene Ontology:
Molecular function: protein binding; serine-type endopeptidase inhibitor activity
Biological process: negative regulation of angiogenesis; positive regulation of neurogenesis; cellular response to cobalt ion; cellular response to dexamethasone stimulus; cellular response to glucose stimulus; cellular response to retinoic acid; kidney development; negative regulation of endothelial cell migration; negative regulation of gene expression; ovulation cycle; positive regulation of neuron projection development; response to acidic pH; response to arsenic-containing substance; response to peptide; retina development in camera-type eye; short-term memory
Cellular component: extracellular exosome; extracellular matrix; extracellular region; axon; axon hillock; basement membrane; melanosome; neuronal cell body; perinuclear region of cytoplasm
Genetic constraint (gnomAD): Loss-of-function variants: 29 observed, 37.29 expected, observed/expected ratio (o/e) 0.78, 90% interval 0.58 to 1.06. The upper end of that interval is the gene's LOEUF score, 1.06, which puts it in group 4 of 6, group 1 being the genes least tolerant of losing a copy. Missense variants: 553 observed, 544.61 expected, observed/expected ratio (o/e) 1.02, 90% interval 0.95 to 1.09. Synonymous variants: 281 observed, 232.19 expected, observed/expected ratio (o/e) 1.21, 90% interval 1.1 to 1.34.
Homologues: Orthologues: chimpanzee SERPINF1 (99% identical), macaque SERPINF1 (95% identical), dog SERPINF1 (90% identical), pig SERPINF1 (88% identical), mouse Serpinf1 (86% identical), rabbit SERPINF1 (85% identical), guinea pig SERPINF1 (83% identical), rat Serpinf1 (83% identical), tropical clawed frog serpinf1 (55% identical), zebrafish serpinf1 (38% identical). Paralogues in human: SERPINF2 (28% identical), SERPINA3 (24% identical), SERPING1 (24% identical), SERPINA4 (24% identical), SERPINA6 (23% identical), SERPINA1 (23% identical), SERPINA10 (23% identical), SERPINH1 (23% identical), SERPINA7 (22% identical), SERPINA5 (22% identical), SERPINB3 (22% identical), SERPINB5 (22% identical), and 24 more.
Diseases named in the same sentence as SERPINF1 in open-access papers:
SERPINF1 is named in the same sentence as 265 diseases in open-access papers, as found by Europe PMC text mining. Sharing a sentence is not in itself a finding about the gene and the disease. The quoted sentences say what the papers report.
diabetes (51 papers, 2007 to 2025). "While elevated levels of SERPINF1 have been reported in patients with diabetes and associated microvascular complications, a study showed that SERPINF1 was a critical negative regulator of tumor invasion in the pancreas." (PMID 32545216, 2020). "Interestingly, several DEGs identified in this study had been reported to be associated with the occurrence and progression of diabetes, including SERPINF1, PID1, IL1R1 and PGC." (PMID 39845878, 2024). "Two genes were very proximal to each other located on chromosome 17p13.3 ‐ rs12150053 near SERPINF1 and rs659366 near UCP2, suggesting a possible hotspot related to susceptibility to type 2 diabetes mellitus in the region." (PMID 39561140, 2024).
Insulin resistance (28 papers, 2012 to 2025). Increased resistance towards insulin, that is, diminished effectiveness of insulin in reducing blood glucose levels. "Our finding that the protein abundance of secreted SERPINF1 was associated with higher adiposity and reduced muscle mass, walking speed, stair climbing, and leg power supports this link, as insulin resistance and elevated inflammation are often associated with aging, sarcopenic skeletal muscle." (PMID 40502786, 2025). "SERPINF1 is a neurotrophic protein among the most abundant glycoproteins secreted by adipocytes and its genetic variants have been previously associated with obesity, insulin resistance, overall adiposity and circulating leptin levels." (PMID 34685777, 2021). "Although no gender-based alterations of this protein have been reported in the eye, SERPINF1 level was elevated in serum samples of women with polycystic ovary syndrome associated with insulin resistance and reduced in peritoneal fluid of women with endometriosis." (PMID 28273097, 2017). "PEDF (encoded by SERPINF1), a known adipokine, has been implicated in the pathophysiology of type 2 diabetes due to its strong association with cardiometabolic risk factors such as obesity-associated inflammation and insulin resistance." (PMID 40502786, 2025). "Indeed, reduced expression levels of Serpinf1 correlated with improved insulin sensitivity and reduced insulin resistance." (PMID 28575190, 2018).
breast carcinoma (27 papers, 2014 to 2025). "For example, SERPINF1 showed anti-tumor effects by inhibiting angiogenesis in melanoma, cholangiocarcinoma, and breast cancer." (PMID 36980858, 2023). "In Roquin2-overexpressing MDA-MB-468 and MCF7 cells, we found that proangiogenic factors mRNA, including PDGFC, ENG, EDN1, and VEGFB, were downregulated in two breast cancer cells, while the mRNA expression of antiangiogenic genes, including TIMP1/3, SERPINF1, and ANGPTL4 were upregulated." (PMID 34345214, 2021).
melanoma (27 papers, 2009 to 2025). A malignant, usually aggressive tumor composed of atypical, neoplastic melanocytes. "NRAS Q61L melanomas were most enriched for modules 7 (C19orf10, ARF4, KDELR2), 13 (TIMM50, ZBED3-AS1, SERPINF1), and 15 (RAP1GAP, OCA2, PAICS)." (PMID 39796775, 2025).
Obesity (27 papers, 2012 to 2025). Accumulation of substantial excess body fat. "The derived allele frequency of rs560826688 is 0.031, and belongs to LRP5 involved in hypertension, and derived allele frequency of rs563254260 is 0.026 and lies in SERPINF1 which relates to obesity and hypertension." (PMID 29420653, 2018). "SERPINF1 has already been associated with obesity before but our study quantitatively establishes its fast downregulation in response to weight loss." (PMID 28007936, 2016). "We observed an increase in the amount of SERPINF1, a protein known to be secreted by adipocytes, in both obesity and T2D." (PMID 41441338, 2025). "Pathway analysis revealed that obesity alters small EV miRNAs that target inflammatory (SERPINF1, death receptor and Gαi) and growth pathways (Wnt/β‐catenin, PTEN, PI3K/AKT and IGF‐1)." (PMID 35293040, 2022). "The following seven proteins are present in higher amounts in the Obesity group compared with the Control group: hemopexin—HPX, complement factor B—CFB, complement C3—C3, kininogen-1—KNG1, vitronectin—VTN, pigment epithelium-derived factor—SERPINF1 and beta-Ala-His dipeptidase—CNDP1." (PMID 41441338, 2025).
prostate carcinoma (24 papers, 2009 to 2025). A carcinoma that arises from epithelial cells of the prostate gland. "The enriched genes included CD4 in cervical cancer, VPS52, NUP62, CRYGD, IL34, GATA3 in prostate cancer and F11, TXNIP, KIT, ASGR2, SERPINF1 in liver cancer, which also provide insight into the molecular mechanisms underlying cancer progression and the potential impact on patient survival." (PMID 37393582, 2023).
osteogenesis imperfecta (23 papers, 2015 to 2025). Osteogenesis imperfecta (OI) comprises a heterogeneous group of genetic disorders characterized by increased bone fragility, low bone mass, and susceptibility to bone fractures with variable severity. "Osteogenesis imperfecta type VI is a rare autosomal recessive disorder characterized by bone fragility and defective mineralization, caused by pathogenic variants in the SERPINF1 gene." (PMID 40649977, 2025). "SERPINF1 (PEDF) is implicated in type VI osteogenesis imperfecta (OI), for which several null recessive mutation variants have been reported." (PMID 40871084, 2025). "SERPINF1 gene variants lead to a severe type of osteogenesis imperfecta (OI) attributed to defects in the matrix mineralization." (PMID 37425194, 2023). "In regard to a musculoskeletal disease, the heritable disorder osteogenesis imperfecta, characterized by bone fragility and low bone mass, is caused by mutations in the SERPINF1 gene." (PMID 35606786, 2022). "Further investigation, including a panel of genes associated with osteogenesis imperfecta, revealed that the patient is a heterozygous carrier of a SERPINF1 variant." (PMID 34283899, 2021). "Becker J., Semler O., Gilissen C., Li Y., Bolz H.J., Giunta C., BergmannC., Rohrbach M., Koerber F., Zimmermann K. Exome sequencingidentifies truncating mutations in human SERPINF1 inautosomal-recessive osteogenesis imperfecta." (PMID 33659802, 2020). "Recently, mutations of the SERPINF1-gene resulting in loss-of-function of PEDF cause the recessive osteogenesis imperfecta type IV that is characterized by a severe skeletal phenotype with increased risk of fractures and skeletal deformities." (PMID 28191465, 2017). "Mutations in SERPINF1 are already known to underlie one recessive form of the connective tissue disorder osteogenesis imperfecta (OI) type VI (MIM: 613982)." (PMID 27056980, 2016). "A loss-of-function alteration in SERPINF1 has been demonstrated to cause osteogenesis imperfecta type VI in humans while variants in SERPINH1 have been associated with ostogenesis imperfecta in both humans and dogs." (PMID 25875171, 2015). "Furthermore, dysregulated expression of Serpinf1 or the loss of Serpinf1 is reported to result in osteogenesis imperfecta (OI) type VI." (PMID 36834981, 2023). "SERPINF1 is the pathogenic gene of Osteogenesis imperfecta type VI." (PMID 37260987, 2023). "Homozygous mutations in Serpinf1 cause deficiency of PEDF, which leads to osteogenesis imperfecta." (PMID 33828460, 2021). "A form of osteogenesis imperfecta, a heritable bone dysplasia characterized by bone fragility and deformity and growth deficiency with a mineralization defect, is caused by mutations in SERPINF1." (PMID 28680659, 2017). "In patients with osteogenesis imperfecta type VI, a disease characterized by low bone mass and reduced bone strength, a homozygous frame-shift mutation in exon 4 or a termination mutation in exon 8 in the SERPINF1 gene is detected, resulting in undetectable levels of PEDF protein in the circulation." (PMID 25881671, 2015). "There is an opposing relationship between TGFβ1 and PEDF in a study on type VI osteogenesis imperfecta pathogenesis using Serpinf1 (−/−) mouse osteoblasts." (PMID 37108600, 2023). "In F1, the proband (III-1) had microphthalmia and osteogenesis imperfecta, with variants in STRA6 and SERPINF1 respectively." (PMID 34276053, 2021). "Recently, an atypical case of osteogenesis imperfecta type VI was reported in which the patient had normal serum PEDF levels and correct SERPINF1 gene sequence, but a heterozygous single point mutation in the IFITM5 gene." (PMID 25881671, 2015).
metabolic syndrome (21 papers, 2008 to 2025). A cluster of metabolic risk factors for CARDIOVASCULAR DISEASES and TYPE 2 DIABETES MELLITUS. "Elevated levels of Serpinf1 may serve as a regulator of metabolic syndrome and prolonged administration leads to adipose tissue lipolysis and reduced insulin sensitivity." (PMID 28575190, 2018).
retinal degeneration (20 papers, 2012 to 2025). Degeneration of the retina. "In rd10/Serpinf1−/−, ONL preservation was less marked, likely due to the increased retinal degeneration susceptibility caused by Serpinf1 gene deletion." (PMID 39109177, 2024). "We also used the rd10/Serpinf1−/−mouse model, in which pigment epithelium-derived factor (PEDF) deficiency increases retinal degeneration susceptibility." (PMID 39109177, 2024). "It was also shown that the lack of PEDF in Serpinf1 null × rd10 mice resulted in an increased susceptibility to retinal degeneration compared to that of rd10 mice." (PMID 39457573, 2024).
hepatocellular carcinoma (18 papers, 2011 to 2025). A malignant tumor that arises from hepatocytes. "SERPINF1 could increase the intracellular accumulation of free fatty acids, thereby promoting the proliferation of hepatocellular carcinoma cells." (PMID 36980858, 2023). "Meanwhile, extracellular SERPINF1 could suppress tumor angiogenesis in vivo, which explained why SERPINF1 did not affect the prognosis of patients with hepatocellular carcinoma." (PMID 36980858, 2023).
glioma (17 papers, 2011 to 2025). A benign or malignant brain and spinal cord tumor that arises from glial cells (astrocytes, oligodendrocytes, ependymal cells). "The association between SERPINF1 upregulation and Notch signaling activation in glioma cells would be worthy of further investigation." (PMID 36980858, 2023). "To explore the signaling pathways associated with SERPINF1 expression, we classified the glioma cells of cluster one as the high-SERPINF1 cluster and the rest as the low-SERPINF1 cluster." (PMID 36980858, 2023). "Furthermore, the association between SERPINF1 expression and glioma stemness was investigated." (PMID 36980858, 2023). "Importantly, the prediction of TFs may improve our understanding of the mechanisms underlying the transcriptional upregulation of SERPINF1 in glioma." (PMID 36980858, 2023). "We performed the SCENIC analysis at the single-cell level to explore the transcriptional regulation of SERPINF1 in glioma cells." (PMID 36980858, 2023). "Spearman’s correlation analysis showed that the expression of SERPINF1 was positively correlated with the stemness index in glioma." (PMID 36980858, 2023). "Differential expression analysis of SERPINF1 was performed in 666 gliomas from TCGA and 897 gliomas from CGGA." (PMID 36980858, 2023). "Taken together, these findings suggested that increased expression of SERPINF1 predicted poor prognosis in glioma patients." (PMID 36980858, 2023). "In the present study, we analyzed the prognostic value of SERPINF1 in three independent glioma datasets." (PMID 36980858, 2023). "The top five TFs with the highest correlations in both datasets consisted of STAT1, MEOX2, CREM, NR2F2, and IRF3, indicating that they were likely to regulate the expression of SERPINF1 in glioma." (PMID 36980858, 2023). "The results showed that STAT1, CREM, and NR2F2 were the most likely upstream TFs of SERPINF1 in glioma." (PMID 36980858, 2023). "To evaluate the effect of SERPINF1 on glioma cells, we knocked down the expression of SERPINF1 with siRNA in glioma cell lines A172 and LN18." (PMID 36980858, 2023). "The feature plot showed that SERPINF1 was significantly highly expressed in the glioma cells of cluster one." (PMID 36980858, 2023). "In this study, we assessed the role of SERPINF1 in the clinical stratification of glioma patients in three independent datasets." (PMID 36980858, 2023). "Our results showed that a higher expression of SERPINF1 correlated with a poor overall survival rate in glioma patients (hazard ratio: 4.061 in TCGA, 2.017 in CGGA, and 1.675 in GSE16011, p < 0.001)." (PMID 36980858, 2023). "The stemness index of gliomas in the high-SERPINF1 group was significantly higher than that of gliomas in the low-SERPINF1 group." (PMID 36980858, 2023). "In our study, we found that SERPINF1 expression was significantly upregulated when glioma cells were induced into GSCs." (PMID 36980858, 2023). "Bioinformatics analysis revealed that SERPINF1 expression was positively correlated with glioma stemness." (PMID 36980858, 2023). "Glioma samples were stratified into high- and low-SERPINF1 groups based on the median expression level of SERPINF1." (PMID 36980858, 2023). "Cellular functional experiments revealed that SERPINF1 knockdown significantly suppressed the proliferation, invasion, and migration of glioma cells A172 and LN18." (PMID 36980858, 2023). "The RT-qPCR revealed that SERPINF1 expression was significantly upregulated when glioma cells were induced into GSCs." (PMID 36980858, 2023). "In a nutshell, our study uncovered the prognostic significance and molecular functions of SERPINF1, suggesting that SERPINF1 is a candidate therapeutic target for glioma." (PMID 36980858, 2023). "Moreover, in vitro experiments were conducted to evaluate the roles of SERPINF1 in the proliferation, invasion, migration, and stemness of glioma cells." (PMID 36980858, 2023).